TMEM40 (transmembrane protein 40)
Synonyms: FLJ11036
Tractability: Antibody: UniProt predicts a signal peptide or a membrane-spanning region; the Human Protein Atlas places it where antibodies can reach.
Gene: Protein-coding gene on chromosome 3 (12,733,528 to 12,769,457, reverse strand). Ensembl gene ENSG00000088726.
Subcellular location: Membrane
Subcellular location (Human Protein Atlas): Plasma membrane; Cytosol
Gene Ontology:
Molecular function: protein binding
Cellular component: membrane
Genetic constraint (gnomAD): Loss-of-function variants: 34 observed, 42.65 expected, observed/expected ratio (o/e) 0.8, 90% interval 0.61 to 1.06. The upper end of that interval is the gene's LOEUF score, 1.06, which puts it in group 4 of 6, group 1 being the genes least tolerant of losing a copy. Missense variants: 296 observed, 290.19 expected, observed/expected ratio (o/e) 1.02, 90% interval 0.93 to 1.12. Synonymous variants: 106 observed, 111.92 expected, observed/expected ratio (o/e) 0.95, 90% interval 0.81 to 1.11.
Homologues: Orthologues: chimpanzee TMEM40 (98% identical), macaque TMEM40 (86% identical), pig TMEM40 (80% identical), rat Tmem40 (76% identical), dog TMEM40 (74% identical), mouse Tmem40 (70% identical), guinea pig TMEM40 (69% identical), tropical clawed frog tmem40 (27% identical).
Diseases named in the same sentence as TMEM40 in open-access papers:
TMEM40 is named in the same sentence as 20 diseases in open-access papers, as found by Europe PMC text mining. Sharing a sentence is not in itself a finding about the gene and the disease. The quoted sentences say what the papers report.
bladder cancer (5 papers, 2018 to 2025). "Previous studies suggested that TMEM40 expression level was significantly associated with clinicopathological parameters including histological grade, clinical stage and pT status of bladder cancer." (PMID 29351801, 2018). "TMEM40 has been found to be a potential biomarker in patients with Bladder cancer, serving as an oncogene and a possible therapeutic target." (PMID 39484215, 2024). "Our previous finding suggested that the expression of TMEM40 in bladder cancer was significantly related to the pathologic grade, clinical stage, histological grade and pT status of bladder cancer." (PMID 37052818, 2023). "In this study, we initially explored TMEM40 mRNA and protein expression and the correlation with malignant behavior, confirmed its potential role in proliferation, migration, and invasion of bladder cancer cells in vitro and tumorigenicity in vivo." (PMID 29351801, 2018). "In this study, we identified the role of TMEM40 in the tumorigenesis of bladder cancer and found that it was upregulated in bladder cancer tissues and cell lines, compared with their normal counterparts." (PMID 29351801, 2018). "Given the role of TMEM40 in bladder cancer, it is important to clarify the abundance of TMEM40 expression in CC and whether it can play a role in the regulation of cell malignant behavior in CC, as well as its unknown regulatory molecular mechanism." (PMID 37052818, 2023).
cervical cancer (2 papers, 2023 to 2025). A primary or metastatic malignant neoplasm involving the cervix. "Moreover, recent studies have reported that lower TMEM40 expression is associated with better overall survival in cervical cancer, suggesting that TMEM40 is a potential prognostic indicator." (PMID 37052818, 2023). "The expression of TMEM40 in CC tissues was investigated with IHC and the results indicated that TMEM40 expression varied from normal cervical to cervical cancer tissues." (PMID 37052818, 2023). "Recent studies indicated that transmembrane protein 40 (TMEM40) is associated with several types of cancers but is not clear in cervical cancer (CC)." (PMID 37052818, 2023).
acute myeloid leukemia (1 paper, 2022). Acute myeloid leukemia (AML) is a group of neoplasms arising from precursor cells committed to the myeloid cell-line differentiation. "Further, an in-depth literature analysis revealed that several of these genes play important roles in cancer (CDCA3, ECEL1, EN1, HLA-DMB, SPRR2A, TMEM40) including acute myeloid leukemia (CDCA3, HLA-DMB, RPL18A, PF4, PRG3) and T cell acute lymphoblastic leukemia (TLX3)." (PMID 35008420, 2022).
lymph node metastasis (1 paper, 2023). "High expression of TMEM40 was markedly associated with lymph node metastasis (p = 0.010) and tumor size (p = 0.006)." (PMID 37052818, 2023).
renal clear cell carcinoma (1 paper, 2022). "Also, miR-138-5p functioned as a tumor-suppressive factor by targeting transmembrane protein 40 (TMEM40) directly in renal clear cell carcinoma." (PMID 35938021, 2022).
tumor (6 papers, 2018 to 2023). "Subsequently, we selected CaSki and HeLa cells to overexpress or knockdown TMEM40 in vitro to observe its effect on tumor progression." (PMID 37052818, 2023). "The results revealed that the TMEM40 elevation in CC tissues and cell lines was closely correlated with tumor size and lymph node metastasis in clinical patients." (PMID 37052818, 2023). "To further investigate the in vivo tumor inhibition effect of TMEM40 knockdown, we subcutaneously injected SiHa cells transfected with TMEM40 shRNA and shNC plasmid in nude mice to establish the xenograft models." (PMID 37052818, 2023). "Analysis of Gene Expression Profiling Interactive Analysis (GEPIA) site suggested that TMEM40 levels in tumor tissue (N = 306) were observably higher than those in normal cervical tissue (N = 13)." (PMID 37052818, 2023). "After 4 weeks of modeling, tumor size and weight were significantly lower in the shRNA TMEM40 group than shNC group." (PMID 37052818, 2023). "In mouse xenograft models for BCa, TMEM40 knockdown was also found to considerably retard tumor formation and subsequent tumor growth." (PMID 29351801, 2018). "In addition, the tumor growth rate of TMEM40 shRNA group was distinctly slower than that of shNC group." (PMID 37052818, 2023). "At present, little is known about the mechanism of TMEM40 in tumor progression." (PMID 37052818, 2023). "TMEM40 silencing could dramatically suppressed cell proliferation, inhibited cell migration and decreased tumor growth." (PMID 34112093, 2021). "Furthermore, from the Gene Expression Profiling Interactive Analysis (GEPIA), we also found that the level of TMEM40 in the tumor tissues (N = 404) was significantly higher than that in the controlled bladder tissues (N = 28) (P < 0.05)." (PMID 29351801, 2018). "In addition, TMEM40 silencing dramatically decreased tumor growth in mice models." (PMID 37052818, 2023). "Consistently, in vivo data showed that TMEM40 silencing could dramatically decreased tumor growth." (PMID 29351801, 2018). "There were also genes that are of insignificant expression in tumor cells that increase in expression in KO cells, e.g. THBS3, IL2RG, SPRR3, TGM2, HMOX1 and TMEM62 or are lower in expression in tumor cells and significantly decreased in KO cells such as MAN1A1, CES1, STCBP6, SIVA1 and TMEM40." (PMID 31797958, 2019).
cancer (4 papers, 2018 to 2023). A tumor composed of atypical neoplastic, often pleomorphic cells that invade other tissues. "Real-time quantitative RT-PCR (qRT-PCR) and western blot (WB) were used to examine the expression levels of TMEM40 in BCa tissues, paired non-cancer tissues and cell lines." (PMID 29351801, 2018). "From the expression of TMEM40 RNAseq data of the Cancer Genome Atlas (TCGA), we found that TMEM40 expression levels was significantly increased in BCa and other organ cancers compared with their controls (N = 30)." (PMID 29351801, 2018).
TMEM40 also shares sentences with these, for which no sentence is quoted: chondrosarcoma (1 paper); cutaneous squamous cell carcinoma (1); gallbladder cancer (1); gastric cancer (1); hepatocellular carcinoma (1); infection (1); melanoma (1); pancreatic cancer (1); Parkinson disease (1); psoriasis (1); sarcoma (1); schizophrenia (1); tongue squamous cell carcinoma (1).